MTOR (mechanistic target of rapamycin kinase)
Diseases named in the same sentence as MTOR in open-access papers (continued):
Sharing a sentence is not in itself a finding about the gene and the disease.
glioblastoma (continued). "Ongoing research and meticulously planned clinical trials are essential for fully realizing the potential of mTOR inhibitors as an effective therapeutic strategy for glioblastoma patients." (PMID 37834408, 2023). "Recently, a number of studies have shown that downregulation of the pro‐survival mTOR pathway can prevent autophagosome fusion to lysosomes at later time points to induce the autophagic death of glioblastoma cells." (PMID 37539490, 2023). "It is imperative that discovering reliable predictive biomarkers for mTOR inhibitors in glioblastoma is challenging due to the complexity and heterogeneity of the disease." (PMID 37834408, 2023). "As one of the major downstream targets of the PI3K/AKT signaling pathway, the mammalian target of rapamycin (mTOR) signaling is dysregulated in many cancers, including glioblastoma." (PMID 37108511, 2023). "Several mTOR inhibitors, such as rapamycin and its analogs (rapalogs, Torin-1), have been developed and tested in preclinical and clinical studies for glioblastoma treatment." (PMID 37834408, 2023). "It has been reported that mTOR activation increases SLC7A11 protein levels by suppressing lysosomal degradation in glioblastoma cells, and inhibition with Torin 1 reduced the protein levels of SLC7A11." (PMID 36856826, 2023). "The target of rapamycin (mTOR) is crucial in several signaling pathways involved in glioblastoma cell growth, proliferation, and survival, making mTOR an exciting target for drugs such as MET and RES." (PMID 37444478, 2023). "The overexpression of growth factor receptors platelet-derived growth factor receptor (PDGFR) and their ligands vascular endothelial growth factor (VEGF) also activate the mTOR pathway in glioblastoma." (PMID 37834408, 2023). "Another promising therapy is the combination of CDK4/6 and PI3K/mTOR inhibitors for the treatment of recurrent glioblastoma." (PMID 36998447, 2023). "Nonetheless, ongoing research and development efforts in this area show significant potential for enhancing the delivery and efficacy of mTOR inhibitors and improving glioblastoma treatment outcomes." (PMID 37834408, 2023). "As previously stated, multiple genes of the PI3K/AKT/mTOR signaling pathway are commonly altered in human cancers, such as glioblastomas, making it a clinically relevant molecular therapeutic target." (PMID 37998723, 2023). "Pharmacological inhibition of DNA-PKcs with the DNA-PKcs inhibitor NU7441 reduced GSC tumorsphere formation mTORC1/2 inhibitors of KU - 0063794 can inhibit PI3K-Akt-mTOR signaling in glioblastoma and reduce cell proliferation." (PMID 36647156, 2023). "The dysregulated mTOR signaling in glioblastoma drives various cellular processes that promote tumor growth." (PMID 37834408, 2023). "It is crucial to carefully interpret the results of these clinical trials due to potential variations in the overall efficacy of mTOR inhibitors in glioblastoma." (PMID 37834408, 2023). "As standalone agents, mTOR inhibitors have demonstrated limited clinical activity in glioblastoma and other cancers." (PMID 37834408, 2023). "A phase 1 trial for many solid tumors is currently underway for NVP-BEZ235, a dual PI3K family and mTOR inhibitor that has demonstrated effectiveness in glioblastoma." (PMID 37834408, 2023). "Temozolomide and the dual PI3K/mTOR inhibitor XL-765 have been demonstrated to be effective against glioblastoma." (PMID 37834408, 2023). "Glioblastomas are characterized by substantial tumor heterogeneity, leading to variable mTOR pathway activation across different tumor subtypes." (PMID 37834408, 2023). "The PI3K/AKT/mTOR pathway is often active in glioblastoma, and suppressing the cell survival of glioblastoma CSCs plays a key role in tumor therapy." (PMID 38089611, 2023). "Preclinical studies investigating the efficacy of mTOR inhibitors in glioblastoma models have shown promising results." (PMID 37834408, 2023).
glioblastoma (continued). "Emerging strategies for targeting mTOR more effectively in glioblastoma aim to address the limitations of current mTOR inhibitors and improve treatment outcomes." (PMID 37834408, 2023). "For instance, the PI3K/AKT/mTOR signaling pathway has a key role in inhibiting apoptosis during glioblastoma." (PMID 37759505, 2023). "Personalized medicine, guided by molecular profiling and mTOR pathway regulators, enhances glioblastoma treatment outcomes." (PMID 37834408, 2023). "Targeting mTOR in glioblastoma presents a series of obstacles that have impeded the widespread use of mTOR inhibitors as standalone therapies." (PMID 37834408, 2023). "The immune profile of glioblastoma patients also influences response to mTOR inhibitors, as mTOR signaling can affect the immune response." (PMID 37834408, 2023). "The potential of mTOR as a therapeutic target in glioblastoma lies in its central role in regulating essential cellular processes critical for tumor growth and survival." (PMID 37834408, 2023). "Combination therapies involving mTOR inhibitors have shown great promise in enhancing the efficacy of mTOR inhibition in glioblastoma and other types of cancer." (PMID 37834408, 2023). "Targeting mTOR remains an attractive therapeutic strategy with the potential to disrupt multiple aspects of glioblastoma growth and progression." (PMID 37834408, 2023). "Integrating these emerging strategies and a deeper understanding of the complex molecular networks involved in mTOR signaling holds the promise of more effective mTOR-targeted therapies for glioblastoma patients." (PMID 37834408, 2023). "For instance, combining mTOR inhibitors with anti-angiogenic agents like bevacizumab or immune checkpoint inhibitors aims to address multiple aspects of glioblastoma pathogenesis and improve overall therapeutic efficacy." (PMID 37834408, 2023). "The mTOR signaling pathway plays a pivotal role in driving tumor growth and progression in glioblastoma." (PMID 37834408, 2023). "The current review comprehensively explores the role of the mTOR signaling pathway in glioblastoma, elucidating insights into its involvement in tumor growth, progression, and treatment resistance." (PMID 37834408, 2023). "Cells from glioblastoma multiforme (GBM) feature up-regulation of the mechanistic Target of Rapamycin (mTOR), which brings deleterious effects on malignancy and disease course." (PMID 36672156, 2023). "Up-regulation of the mechanistic Target of Rapamycin (mTOR) in glioblastoma multiforme (GBM) is established in human patients and experimental models." (PMID 36672156, 2023). "Dual PI3K/mTOR inhibitors that have been explored in pre-clinical glioblastoma models include dactolisib, voxtalisib, and paxalisib." (PMID 37857607, 2023). "Clinical trials and dedicated research endeavors are indispensable for validating and establishing these biomarkers, which are crucial for tailoring personalized treatment approaches for patients with glioblastoma undergoing mTOR inhibitor therapy." (PMID 37834408, 2023). "Serving as a pivotal regulator of cellular growth, mTOR activation fosters glioblastoma cell proliferation, resulting in rapid tumor expansion and angiogenesis." (PMID 37834408, 2023). "U-87MG, glioblastoma cells, showed higher mTOR activity than KINGS-1, and phosphorylation of S6K and AKT was not affected by suppression of FilGAP expression." (PMID 38065968, 2023). "Numerous preclinical studies have demonstrated that mTOR inhibitors, particularly rapalogs like rapamycin and temsirolimus, can effectively inhibit glioblastoma tumor growth in mouse xenograft and orthotopic models." (PMID 37834408, 2023). "Personalized medicine approaches in glioblastoma treatment involve the genetic profiling of mTOR pathway components to identify specific alterations within the signaling cascade or its upstream regulators in individual patients." (PMID 37834408, 2023).
glioblastoma (continued). "The inhibition of mTOR effectively blocks the excessive cell growth and proliferation observed in glioblastoma cells, resulting in reduced tumor growth." (PMID 37834408, 2023). "Combining mTOR inhibitors with anti-angiogenic or immune checkpoint inhibitors addresses multiple aspects of glioblastoma pathogenesis and improves overall therapeutic efficacy." (PMID 37834408, 2023). "By doing so, the review intends to shed light on new therapeutic avenues and potential advancements in glioblastoma treatment through targeting the mTOR pathway." (PMID 37834408, 2023). "A recent study demonstrated that radicicol promoted anoikis in glioblastoma by causing endoplasmic reticulum stress and preventing AKT/mTOR/p3S3K phosphorylation activation, thus confirming that radicicol was closely associated with PI3K/AKT/mTOR and anoikis." (PMID 37547764, 2023). "The mTOR signaling pathway plays a pivotal and intricate role in the pathogenesis of glioblastoma, driving tumorigenesis and proliferation." (PMID 37834408, 2023). "Inhibition of cathepsin S can also inhibit TGF-β-mediated EMT through the PI3K/AKT/mTOR signaling pathway, as well as the invasive growth of glioblastoma." (PMID 37398678, 2023). "Nanotechnology-based drug delivery systems offer promising solutions to overcome the challenges of delivering mTOR inhibitors to the brain and improve their efficacy in glioblastoma treatment." (PMID 37834408, 2023). "In our experiments, SeNPs and SeSo proved to be the most effective in suppressing the mTOR expression in glioblastoma cells, compared to the same concentration of So." (PMID 36768736, 2023). "Despite these limitations, rapalogs have provided valuable insights into targeting the mTOR pathway in glioblastoma and have laid the groundwork for the development of novel mTOR inhibitors." (PMID 37834408, 2023). "Preclinical studies have shown that mTOR inhibitors can induce autophagy in glioblastoma cells by enhancing the cytotoxic effects of mTOR inhibitors." (PMID 37834408, 2023). "This makes identifying and selecting biomarkers vital for selecting suitable candidates for mTOR-targeted therapies in glioblastoma." (PMID 37834408, 2023). "Ibrutinib has also been shown to promote autophagic cell death in glioblastoma by a mechanism that appears to be mediated by the inhibition of the serine/threonine-specific protein kinase/mammalian target of rapamycin (Akt/mTOR) signaling pathway." (PMID 36903645, 2023). "Targeting the mTOR pathway has been explored as a potential treatment strategy to halt glioblastoma growth and overcome resistance to conventional therapies." (PMID 37834408, 2023). "A previous study reported that RIOK2 formed complexes with RIOK1 and mTOR and then enhanced the Akt-signaling pathway in glioblastoma." (PMID 36661680, 2022). "Taken together, our results show that we have identified the YB-1/CCT4/mLST8/mTOR axis as a contributor to glioblastoma growth and suggest a therapeutic approach to target this axis using competitive RNA oligonucleotides." (PMID 35239512, 2022). "The activation of the hepatocyte growth factor/mesenchymal–epithelial transition (MET) pathway is implicated in the progression of glioblastoma, as it activates downstream signaling events including Ras/Raf/MAPK, STAT3, and PI3K/AKT/mTOR." (PMID 35743016, 2022). "Glioblastoma multiforme (GBM) is a lethal brain tumor that features mTOR overexpression and severe autophagy inhibition." (PMID 35326535, 2022). "Our findings suggest that mTOR inhibition by CLD is effective in treating BRAF V600E mutant glioblastomas." (PMID 35159037, 2022). "The decreased levels of mitophagy markers were observed accompanied by the inhibition of the PI3K/Akt/mTOR pathway in the cultured glioblastoma multiforme (GBM) cells treated with solid lipid curcumin particles (SLCP)." (PMID 36365094, 2022).
glioblastoma (continued). "Cedrol combined with the clinical drug temozolomide also exhibits synergistic suppression in glioblastoma by downregulation of AKT/mTOR signaling and chemosensitizes human leukemia K562 and CRC HT-29 cells by destabilizing plasma membrane lipid rafts 30-32." (PMID 36438926, 2022). "A small molecule C11, which specifically inhibited the IRES activity of c-MYC by blocking the interaction of hnRNP A1 and IRES, exerted a synergistic anti-glioblastoma effect in combination with mTOR inhibitor rapamycin or PP242." (PMID 36365147, 2022). "Nevertheless, despite the rationale behind targeting the PI3K/mTOR pathway, the general clinical results of mTOR inhibitors in the treatment of glioblastoma patients have been rather disappointing." (PMID 35743016, 2022). "Ivermectin inhibits cell proliferation via Akt/mTOR phosphorylation and induces G1 arrest in glioblastoma and cervical cancer." (PMID 36091811, 2022). "ZRANB2-AS2 is a novel susceptibility gene for human anthropometric variation and has been demonstrated to be a clinical biomarker in glioblastoma that affects tumor development through mTOR signaling pathways." (PMID 35401751, 2022). "In this study, we discovered that YB-1 can function as a critical activator of mTOR signaling through mediating a self-activated pathway that impairs the protein homeostasis program in glioblastoma." (PMID 35239512, 2022). "An example is represented by glioblastoma, which, due to a significant upregulation of mTOR, presents occlusion of the autophagic pathway." (PMID 35328780, 2022). "The AMPK pathway has been reported to control c-Myc expression through inhibition of the mTOR pathway in some cancer cells, including pancreatic neuroendocrine tumor cells, glioblastomas and leukemias." (PMID 35954273, 2022). "In glioblastoma cells, DGKα production of PA has been associated with inhibition of apoptosis and regulation of hypoxia-inducible factor 1-α (HIF1-α) and mammalian target of rapamycin (mTOR) oncogenic pathways." (PMID 36358678, 2022). "KDELR2 is a poor prognostic factor for glioblastoma and acts as a direct target of HIF-1α, a regulator of p-mTOR as well as the downstream protein in glioblastoma cells." (PMID 36096734, 2022). "We show that this drug combination mitigates the systemic effects of mTOR inhibitors but retains the efficacy of RapaLink-1 in glioblastoma xenografts." (PMID 36104566, 2022). "Mechanistic studies identify that glioblastoma-derived EVs achieve their functions via activating PI3K-Akt-mTOR pathway in mNPCs." (PMID 35022057, 2022). "There are several in vitro works that have shown that curcumin is able to effectively prevent cell proliferation in glioblastoma by disturbing the mTOR pathway." (PMID 35328780, 2022). "The PI3K/Akt/mTOR signaling pathway and Wnt/β-catenin signaling pathway were usually excessively activated to regulate multiple biological process of glioblastoma including cell proliferation and metastasis." (PMID 36234681, 2022). "Some examples of successful treatments of glioblastoma patients with mTOR inhibitors have been reported, such as in the case of a child having a TSC2-mutant glioblastoma who achieved complete remission under everolimus therapy." (PMID 35743016, 2022). "Taken together, these findings uncover a disrupted proteostasis pathway involving a YB-1/CCT4/mLST8/mTOR axis in promoting glioblastoma growth, suggesting that YB-1 is a potential therapeutic target for the treatment of glioblastoma." (PMID 35239512, 2022). "EVA1A inhibits glioblastoma cells proliferation by upregulating autophagy via suppressing the mTOR/RPS6KB1 pathway." (PMID 35743108, 2022). "As can be seen, this analysis revealed downregulation of ErbB (EGFR) and mammalian target of rapamycin (mTOR) signaling in addition to several other pathways that promote the growth and survival of glioblastoma in both cell lines following GZ17-6.02 treatment." (PMID 35456993, 2022).
glioblastoma (continued). "Progesterone induces senescence and inhibits glycolytic metabolism of glioblastoma by inactivating EGFR/PI3K/AKT/mTOR." (PMID 36139919, 2022). "The autophagy inducing effect of lovastatin is mediated by the suppression of the Akt/mTOR signaling pathway in the glioblastoma multiforme (GBM)." (PMID 35387352, 2022). "In glioblastoma, ivermectin inhibits angiogenesis and deactivates the Akt/mTOR signaling pathway following mitochondrial stress and enhanced ROS levels." (PMID 34684095, 2021). "CUR also has an effect in melanoma and glioblastoma based cancer which was observed via increased autophagy and decreased levels of mitophagy markers, in combination with inhibition of the PI3K-Akt/mTOR pathway when treating of glioblastoma cells." (PMID 34299519, 2021). "Successively, levels of phosphorylated mTOR in human drug-resistant glioblastoma cells were reduced by CoCl2." (PMID 34136065, 2021). "Everolimus, a rapamycin derivative, is an orally administered mTOR inhibitor with activity against various tumour types, including glioblastoma." (PMID 33803216, 2021). "A phase II study of temsirolimus, an analogue of the allosteric mTOR inhibitor rapamycin, showed that this agent was clinically effective in 30% patients treated for recurrent glioblastoma." (PMID 32577848, 2021). "The effect of GDC-0980 on the activity of PI3K/mTOR signalling pathway was then investigated in A-172 and U-118-MG glioblastoma cell lines." (PMID 34768941, 2021). "In parallel with an interruption of the PI3K/AKT pathway, CoCl2 weakened phosphorylation of mTOR in human TMZ-resistant glioblastoma cells." (PMID 34136065, 2021). "We performed a targeted data mining in silico assessment, employing the data from the mentioned TCGA and the more recent CGGA, in which we validated the relevance of the mTOR pathway in a glioblastoma stemness and EMT context." (PMID 34575669, 2021). "As a basis for this, tumorigenesis in glioblastoma multiforme is associated with abnormal PI3K/AKT/mTOR signaling, and inhibition of mTOR signaling induces the activity of MAPK(pERK1/2) and MEK1/2." (PMID 34065991, 2021). "As to the mechanisms, the CoCl2-induced hypoxia decreased levels of phosphoinositide 3-kinase (PI3K) and successive phosphorylations of AKT and mammalian target of rapamycin (mTOR) in TMZ-resistant glioblastoma cells." (PMID 34136065, 2021). "Human glioblastoma U87MG cells represent an ideal model to investigate drug induction of autophagy, because in these cells, one hallmark is mTOR upregulation, which in turn leads to autophagy suppression." (PMID 33799468, 2021). "By western blot, TGF-β increased the expression levels of phosphorylation of PI3K, AKT and mTOR in the glioblastoma cell lines." (PMID 33613746, 2021). "In summary, GDC-0980 is a potent small molecule inhibitor of class I PI3K and mTOR kinase with promise for clinical trials in glioblastoma multiforme as either a single agent or in combination with antimitotic agents." (PMID 34768941, 2021). "Deregulated PI3K/AKT/mTOR signalling commonly exists in glioblastoma, making this axis an attractive target for therapeutic manipulation." (PMID 34768941, 2021). "The migration and invasion of human glioblastoma cells was enhanced under hypoxic conditions through the activation of the PI3K/Akt/mTOR pathway by targeting HIF-1." (PMID 34199959, 2021). "We found that Lpd and EGFR mutually co-operate and Lpd interacts with the rapamycin-insensitive companion of mTOR (RICTOR) consequently critically co-regulating glioblastoma invasion and radiation sensitivity." (PMID 34771501, 2021). "It should be mentioned that coibamide A induced autophagosome storage in the human glioblastoma cells via mTOR-independent mechanism." (PMID 34440090, 2021).